HIF1A (hypoxia inducible factor 1 subunit alpha)
Diseases named in the same sentence as HIF1A in open-access papers (continued):
Sharing a sentence is not in itself a finding about the gene and the disease.
cancer (continued). "Utilizing 5 different cancer cell lines infected with 6U-HBR construct, we observe that different cancer cell lines have distinct eYFP signals under the same oxygen levels, which correlate with the total amount of HIF1 α and HIF2 α proteins in these cell lines." (PMID 22132102, 2011). "However, recent experimental evidence from our laboratory has demonstrated differential protein and mRNA expression of HIF1α and HIF2α between the non-stem and cancer stem cell." (PMID 20104230, 2010). "We showed that inhibition of HIF-1α is required, although it may not be sufficient, to mediate the response of cancer cells to EGFR-targeted therapy." (PMID 21209911, 2010). "Our findings justify the development of new derivatives of 1, 9 PA that may be used in combination with cetuximab for cancer treatment through complementary downregulation of HIF-1α without concomitant inhibition of JNK." (PMID 21209911, 2010). "Inhibitors of HIF-1α or TGF-β, which act upstream of multiple target genes, may be more effective and several are under investigation in phase I and II clinical trials for various cancers." (PMID 19727403, 2009). "Our finding agrees with a study of 146 Japanese patients, mainly with distal gastric cancer, and with some published reports showing HIF-1α has no prognostic significance in cervical, colorectal and ovarian cancers." (PMID 17179985, 2007). "HIF-1α was present at higher levels in some cancer cells but not to the extent of Ndrg1." (PMID 15341671, 2004). "In addition, HIF-1α upregulates other genes whose products contribute to cancer cell invasiveness, such as IL-8, VEGF, and matrix metalloproteinase-9 (MMP-9), responsible for proteolytic cleavage of vascular basement membranes, clearing the way for mesenchymal-like cancer cells to disseminate." (PMID 40710312, 2025). "Additionally, studies using cancer cells and vascular endothelial cells have reported that intermittent hypoxic stimulation of cells gradually enhanced HIF-1α expression with each cycle of hypoxia, and HIF-1α was expressed more strongly than it was with sustained hypoxic stimulation." (PMID 40168275, 2025). "Besides the direct targeting of HIF-1α, a significant decrease in HIF-1α at both transcriptional and translational levels in 2-ANPC-treated cancer cells might be due to its previously demonstrated ability to alter microtubule dynamics and inhibit tubulin polymerization." (PMID 41514626, 2025). "In addition to NF-κB and STAT3, astragaloside IV could regulate the expression of various signal pathways and growth factors, such as VEGF, Nrf2, HIF-1α, P13k-AKT, etc.51, which were closely related to cancer progression, suggesting that astragaloside IV was a promising anticancer drug." (PMID 39085255, 2024). "In cancer treatment, angiogenesis can be inhibited by bevacizumab, a monoclonal antibody that targets VEGF, preventing the signaling pathway that results in the proliferation and migration of endothelial cells; however, HIF-1α may contribute to bevacizumab resistance." (PMID 38396737, 2024). "Thus, double-gated regulation of LHS by MYC/EGLN and HIF-1α has potential to elevate intracellular ROS levels, which is a prerequisite for triggering ferroptosis and provides an alternative cell death pathway to kill apoptosis and autophagy resistant MYC-driven cancer cells." (PMID 37450923, 2024). "Additionally, unlike HIF1α or EZH2, GLI-1 was the sole transcription factor activated by integrin-linked focal adhesion kinase, indicating GLI-1 as a key driver of the EZH2-integrin α11 axis operating for cancer stem cell survival and EMT." (PMID 38664825, 2024).
cancer (continued). "Therefore, it has been proposed that CoQ0 inhibits hypoxia-induced ROS-mediated HIF-1α expression and thus attenuates the NLRP3-mediated inflammation, EMT/metastasis, and Warburg effect in HNSCC cells, which have been suggested as possible targets for cancer therapy." (PMID 38904007, 2024). "HIF1α may promote miR-183/96/182 cluster expression in an HBXIP-dependent manner, out of which miR-183 can target VHL mRNAs and inhibit its expression, thereby constitutively promoting HIF1α-driven tumorigenesis and cancer progression in a feedback loop mechanism." (PMID 37583933, 2023). "Furthermore, activation of mTORC1/HIF-1α signaling regulates lactate/proton symporters of MCT1 for lactate import and MCT-4 for lactate export, which mobilize lactate fuel transfer between stromal and cancer cells to sustain energy supply for cancer malignancies." (PMID 36986244, 2023). "lncRNA NDRG1-OT1 may work as a miRNA sponge to particularly inhibit a tumor suppressor miRNA, miR-875-3p, and promote cancer cell proliferation, though functional targets at the downstream of the HIF1α/NDRG1-OT1/miR-875-3p axis have not been established so far." (PMID 37583933, 2023). "However, despite the lack of HIF-1α and reduced expression of glycolytic enzymes, cancer cells maintain glucose uptake through multiple mechanisms, including increased expression of glucose transporters and of creatine biosynthesis to support maintenance of ATP levels." (PMID 37568758, 2023). "In addition to the AMPK pathway, several non-AMPK pathways, such as RAS, AKT, and HIF-1α, may contribute to the anti-cancer effect of metformin." (PMID 35222283, 2022). "Furthermore, several factors have been identified for their crucial role in stimulating cancer-related inflammation, including cytokines (interleukins, TNF-α, TGF-β, and granulocyte macrophage colony-stimulating factor), chemokines, and transcription factors (NF-kB, STAT3, HIF-1-α)." (PMID 35956766, 2022). "Correspondingly, with the involvement of HIF-1α, follicular helper T cell differentiation may be promoted by the E3 ubiquitin ligase VHL via m6A methylation-mediated glycolytic modification, which supports the formation of germinal centers and malignant tumors, such as follicular lymphoma." (PMID 35794625, 2022). "Given that HIF-1α is a main driver of the glycolytic and catabolic state with secretion of monocarboxylates in CAFs, we next aimed to assess whether HIF-1α inhibition with the drug BAY 87-2243 could have an impact on the metabolism of fibroblasts and carcinoma cell aggressiveness in ADT co-cultures." (PMID 35814364, 2022). "By regulating HIF-1A, this mechanism could provide a link between cancer mechanotransduction and metabolism as well as a potential pathway for mechanical cues from the pre-malignant ECM to drive metabolic changes in epithelial cells during the early stages of cancer evolution." (PMID 34209094, 2021). "Therefore, the effect of HIF-1α overexpression might be dependent on the cancer type and presence or absence of other genetic alterations." (PMID 33639646, 2021). "Although the role of the GHET1/VHL/HIF1α axis in apoptosis has not yet been elucidated, HIF1α and cancer metabolism have been shown to play important roles in apoptosis regulation, suggesting the possibility that this axis may also be involved in the phenomenon." (PMID 33996797, 2021). "Furthermore, we did not evaluate the HIF-1α downstream effectors and, hence, their effects on cancer cell biology are unknown." (PMID 33673181, 2021). "However, whether HIF-1α-related pathways are operative under normoxia and whether cancer cells originating from different tissues are dependent of HIF-1α under non-hypoxic stress conditions are questions that remain to be elucidated." (PMID 33396270, 2020).
cancer (continued). "Illogically, however, HIF1A displayed a weak but negative association with DDAH1 in multivariate analysis, an observation that requires further investigation, especially because targeting DDAHs has only recently been proposed as a novel antiangiogenic strategy in cancer." (PMID 32121248, 2020). "Interestingly, c-MYC expression induces angiogenesis in combination with HIF-1α and VEGF and recruits tryptase positive mast cells into the tumor niche, therefore, MYC inhibition may have a potential anti-cancer effect." (PMID 33469537, 2020). "Moreover, COX activity and OxPhos flux have not been directly determined to assess whether HIF-1α indeed may downregulate the mitochondrial function in cancer cells." (PMID 31600993, 2019). "In addition to hypoxia, which is a major driver of CAIX expression by cancer cells, CAIX can also be induced in normoxia by high cell-density-mediated pseudohypoxia, and by hypoxia-independent mechanisms such as lactate- and redox-mediated stabilization of HIF-1α." (PMID 29517989, 2018). "Some factors identified (e.g., NF-κB, STAT3, FOS) are known to be involved for transformation in our model, others (e.g., CEBPB, HIF1a, ETS2, FHL2, TCF7L2, and NFE2L2) have been described as oncogenes in other settings, and some proteins (BHLHE40 and MAFB) have not been well linked to cancer." (PMID 29802342, 2018). "Furthermore, HIF-1α has been demonstrated to act as a key regulator in glycolysis, HIF-1α is the best-known transcriptional regulators controlling expression of glycolysis genes, such as HK1, HK2, and LDHA, whose expression levels are highly elevated in cancer cells." (PMID 29137372, 2017). "Thus, we could not exclude the possibility that in addition to the HIF-1α suppression, some other mechanism(s) or target(s) may contribute to the anti-cancer activities exerted by Q6." (PMID 26649750, 2015). "In conclusion, MMP2 expression may be regulated by HIF-1α in HCC, and the hypoxic microenvironment in HCC tissues may induce nuclear transcription factor HIF-1α overexpression, which possibly activates MMP2 and participates in the invasion and metastasis of the cancer cells." (PMID 25013467, 2014). "In this regard, we demonstrate that HIF-1α/GPER signaling mediates the up-regulation of VEGF as well as the endothelial tube formation, suggesting that this transduction pathway may be involved in the intricate stimulatory responses to hypoxia within the cancer stroma." (PMID 23947803, 2013). "We further show that a loss of PHD3 expression does not correlate with an increase in HIF-1α protein levels or an increase in the transcriptional activity of HIF, suggesting that loss of PHD3 may convey a selective advantage in some cancers by affecting pathway(s) other than HIF." (PMID 21297970, 2011). "Clarification of the conditions or stimulations required for specific HIF-1α activities (for instance, promoting or suppressing the expression of specific genes or gene sets) may greatly help the development of HIF-1α-targeted therapeutics and the monitor of cancer progression and prognosis." (PMID 20932347, 2010). "HIF-1α expression was elevated in cancer tissues versus non-cancerous tissues, with hypoxic conditions differentially regulating ATXN3 via HIF-1α across cell lines." (PMID 41507147, 2026). "Although HIF-1α and HIF-2α have been widely shown to be overexpressed in many cancer types, they often play nonoverlapping and sometimes contrasting roles in cancer development and progression." (PMID 41413686, 2025).
cancer (continued). "Then came the discovery that lactate controls the proteasomal degradation of hypoxia-inducible factor-1α (HIF-1α), thus increasing HIF-1α protein levels in cancer cells even in the presence of normal oxygen, a condition now described as “pseudohypoxia”." (PMID 38339256, 2024). "With respect to CSCs, a study investigating glioblastoma stem cells demonstrated differential expression of HIF-1α and HIF-2α in stem and non-stem cancer cell populations." (PMID 37614497, 2023). "HIF-1α activation triggers transcription of many genes (such as GLUT4, CAIX, HXII, and RAGE) that are involved in metabolic reprogramming and survival of cancer cells, as well as EMT genes such as TGF, NF-kB, and Notch." (PMID 36769076, 2023). "HIF-1α induces the expression of P4HA1, P4HA2, PLOD1, and PLOD2 in different cancer and non-cancer cell lines, and enhanced activities of these enzymes are associated with increased collagen deposition in cancer tissue." (PMID 37490147, 2023). "Such cooperation is also observed for HIF2α, although unlike HIF1α, HIF2α is better known to promote MYC activity in cancer." (PMID 37601651, 2023). "No significant change was found in CD133/HIF-1α (S) ratio in MPE patients compared to the control group, perhaps due to inadequate amount of free CD133 in the blood of cancer patients." (PMID 37841777, 2023). "Alternatively, while cancer cells are distal from the oxygen source, MYC, in cooperation with HIF-1α can suppress mitochondrial respiration without affecting the mitochondrial biogenesis process." (PMID 37762231, 2023). "Although local RT did not significantly alter HIF-1α expression in our experiment, RT is a known potent inducer of hypoxia, which activates HIF-1α in cancer cells." (PMID 37685868, 2023). "The DCA-induced PDK1 suppression was partially dependent on hypoxia-inducible factor-1α (HIF-1α), a transcriptional regulator of PDK1, in cancer cells but not in L6 myotubes." (PMID 34445316, 2021). "Although hypoxia and HIF-1α are known to be important in cancer, LW1497 has not been therapeutically applied to cancer yet." (PMID 34829545, 2021). "Therapeutic strategies to disrupting HIF-1α and the related downstream genes would be able to switch TME for kill and clearance by NK cells and macrophages and improve cancer immunotherapies in non-responder HCC patients." (PMID 34557407, 2021). "ASS1 and ARG2 expression by cancer cells or by CAFs were not related to the expression of HIF1α, LDH5, or CA9 by cancer cells." (PMID 34344457, 2021). "Therefore, whereas exosomes secreted by normal fibroblasts might impair cancer progression by downregulating DNMT1 and HIF1α in cancer cells through delivering miR-148b and miR-320a, the lack of inhibition by CAFs-derived exosomes could boost the cancer progression." (PMID 34852849, 2021). "We found that the non-degradable HIF-1α mutants and TGF-β synergistically promoted glycolysis and proliferation of cancer cells under normoxic conditions, which was completely consistent with previous results." (PMID 34930376, 2021). "Importantly, overexpression HIF‐1α dose not to completely abrogate alpinetin‐induced apoptosis, these findings indicated that other pathways may also contribute to alpinetin‐induced cancer phenotypic changes." (PMID 32562470, 2020). "In fact, in response to HIF-2α knockdown, but not HIF-1α knockdown, the SW1353 transcriptome was negatively enriched in regard to the Cancer stem cell gene set." (PMID 33024108, 2020). "Recently, this transporter was shown to induce the hypoxia-independent accumulation of hypoxia-inducible factor 1 alpha (HIF-1α) and inhibit both apoptotic and nonapoptotic death in cancer cells." (PMID 32053908, 2020). "The increase in PpIX accumulation by inhibiting RSKs, HIF-1α, or ABCB1 in the human cancer cell lines was not as robust as that by inhibiting MEK." (PMID 33335181, 2020). "HIF-1α is a well characterized member of the HIF family and is upregulated in various cancers compared with nontumorous tissues." (PMID 32111982, 2020).
cancer (continued). "Positive correlation with cancer-promoting genes BCL2, BCLxL, HIF1A, VEGFA, ACTA2, CCL2, PTGS2, and CDKN1A, but not Ki67, was demonstrated, particularly for ILs’ receptors." (PMID 32512917, 2020). "In the absence of PTEN, HIF-1α is able to act as a transcription factor for VEGFA, increasing angiogenesis, as well as activating other pathways that promote aggressive cancer phenotypes." (PMID 32707933, 2020). "In particular, at least two players undergo significant changes in cancer cells deprived of CI, converging toward the promotion of PHD activity and HIF-1α destabilization regardless of hypoxia, one of them being the accumulation of α-KG30." (PMID 30796225, 2019). "Unlike HIF‐1α that has been extensively investigated, it is little known about the function of its regulatory partner HIF‐1β in cancer, including MM." (PMID 29926531, 2018). "For instance, administration of a series of dual inhibitors of HIF-1α and STAT3 (in the absence of anticancer agent) resulted in significant anti-proliferative activity across a panel of various cancer cell lines." (PMID 30347860, 2018). "Persistent activation of STAT3 contributes to HIF-1α and VEGF expression in cancer cells and other non-ECs." (PMID 28978186, 2017). "Previous studies have indicated a negative role for ANGPTL4 in other cancer types, and ANGPTL4 has previously been shown to be activated by HIF-1α and to confer protection against hypoxia-induced apoptosis in cell lines." (PMID 26205780, 2015). "Subsequently, we measured the levels of HIF-1α and VEGF protein expression in HUVECs and SKOV-3 cancer cells (data not shown) exposed to normoxia or 1% O2 hypoxia and sMEK1 transfection." (PMID 26378810, 2015). "However, the binding affinities of EGCG to HIF-1α and many other targets are higher than the EGCG plasma peak level in experimental animals administered with high dose of EGCG, raising a concern whether the microRNA regulation by HIF-1α is involved in the anti-cancer activity of EGCG in vivo." (PMID 25559244, 2014). "ARG2 expression in cancer cells was not restricted to areas around necrosis or near CAIX-, SLC2A1-, or HIF-1α-expressing cells (data not shown)." (PMID 23424623, 2013). "Most slides from cancer-free tissue lacked expression of CCND1, CD44, CDH1, EGFR, ERBB2, KIT, keratins, NOTCH1, PAK1, PTGS2, SNAI1, and VIM but showed staining of MUC1, HIF1A, NKX2-1, SFTPC, and STAT3, which were also found in AdCa." (PMID 23028920, 2012). "PKM2, but not PKM1, is prolyl hydroxylated and PKM2, but not PKM1, interacts with HIF-1α, thus providing a molecular basis for the selective effect of PKM2 on HIF-1-mediated transactivation and the Warburg effect in cancer cells." (PMID 21709315, 2011). "In cancer cells PDK expression is upregulated by the HIF1α transcription factor, and HIF1α is not activated in the MCF10HER2 cells that is by comparison only partly transformed." (PMID 21437235, 2011). "In another study, insulin and epidermal growth factor or an inactivating mutation in the tumor suppressor PTEN specifically increased the protein levels of HIF-1α, but not of HIF-1β in human cancer cell lines." (PMID 19384426, 2007). "HIF‐1α and EZH2 interact to form a negative feedback loop that promotes cancer development." (PMID 38072662, 2024). "Here, we report that the antifungal agent ciclopirox olamine (CPX), a potential candidate for drug repurposing in cancer treatment, is able to reprogram gastric non-CSCs into cancer stem-like cells via activation of SOX2 expression and increased expression of C-MYC, HIF-1α, KLF4, and HMGA1." (PMID 37686684, 2023). "However, in cancer cells MYC and HIF1α are not incompatible since many cancer types have both MYC and HIF1α in high levels." (PMID 37601651, 2023). "Along this line, it would be important to assess whether a co-blockade of TIGIT and HIF-1α is as effective as the blockade of TIGIT and PD-1 as a therapeutic possibility for those cancers which are not PD-L1 positive." (PMID 36874131, 2023).